ANG (angiogenin)
Diseases named in the same sentence as ANG in open-access papers (continued):
Sharing a sentence is not in itself a finding about the gene and the disease.
tumor (167 papers, 1988 to 2026). "Recent studies have highlighted the strong association between tumor progression and neoangiogenesis, with the angiopoietin (ANG) family playing a central role in this process." (PMID 40260291, 2025). "According to scRNAseq analysis, ANG was mainly expressed by neoplastic cells and tumor-associated macrophages (TAMs) and was correlated with the initiation and progression of tumor cells and the polarization of TAMs." (PMID 37928479, 2023). "High levels of angiogenin in serum have been associated with poor prognosis in different tumours, and with higher tumour vascularity and the activation of hepatic stellate cells in HCC." (PMID 37896150, 2023). "The stimulation of angiogenin in mCAF after exosome application can also be associated with tumour vascularisation." (PMID 34837514, 2022). "Angiogenin has been implicated in tumor cell proliferation and was found to interact with extracellular matrix proteins, such as fibulin-1." (PMID 33802060, 2021). "In the current study, we found the IHC scores of ANG in recurrent NPC tissues to be significantly higher than those in primary tumour tissues, and ANG expression was significantly associated with tumour recurrence in NPC." (PMID 34512316, 2021). "Similar autocrine stimulation mediated by the hRNase5/ANG-EGFR pair also has potential to occur in the tumor-associated fibroblasts, where both proteins have considerable amounts of expression." (PMID 30449278, 2018). "Angiogenin is a small protein with ribonucleolytic activity and is a potent angiogenic factor implicated in tumor growth." (PMID 24303036, 2013). "We have further shown that DEC1 expression is strongly associated with HIF-1α, the hypoxically induced protein angiogenin and tumour grade, suggesting a role for DEC1 in blocking tumour differentiation and potentially apoptosis." (PMID 15328513, 2004). "Therefore, we identified three SASP-related genes (VGF, IGFBP3, and ANG), established a risk score, and uncovered detrimental and beneficial tumor subtypes based on these genes." (PMID 37624511, 2023). "Thus, we suspect that the upregulation of 5’tiRNA-His-GTG in CRC tissues was probably caused by an increase in ANG in response to the hypoxic environment in tumor tissues." (PMID 33588913, 2021). "Taken together, these results suggest that serum ANG levels are significantly associated with tumors; however, serum ANG levels vary among different tumor types; therefore, more data are needed to verify the existence of an association between ANG levels and different cancers." (PMID 29736193, 2018). "Tumor angiogenesis is regulated by angiogenic factors, some of the most patient angiogenic factors, such as vascular endothelial growth factor and ANG in vivo, are produced by macrophages and other immune cells in the tumor microenvironment." (PMID 40260291, 2025). "AVM and CCMs release and respond to cytokines, such as vascular endothelial growth factors (VEGFs), fibroblast growth factor, angiogenin, and tumor necrosis factor-alpha, that promote neoplasia." (PMID 41458749, 2025). "In conclusion, ANG is important in tumor anti-angiogenic strategies in head and neck tumor therapy, and inhibition of the activity of molecules such as ANG2 shows potential therapeutic benefits." (PMID 40260291, 2025). "Although angiogenin has been shown to promote tumor growth and angiogenesis, its upregulation in the alloreactive immune response has been shown to inhibit apoptosis of CD4+ T cells." (PMID 38245670, 2024). "In various experimental tumor cell models, angiogenin regulates cell proliferation, migration, and adhesion by activating the SAPK/JNK, ERK1/2, and PI3K/AKT pathways in various cells and under different conditions." (PMID 39796700, 2024). "Various angiogenin inhibitors (including enzyme inhibitors, mAbs, siRNAs, and soluble binding proteins) inhibit tumor growth in various animal models; further clinical trials of angiogenin are needed." (PMID 39796700, 2024).
tumor (continued). "CLL cells and tumor-associated stromal cells also produce and secrete FGF-2, TNF-α, CXCL-12, CXCL-2, NGAL, IGF-1, progranulin, and angiogenin." (PMID 39796700, 2024). "Due to its effect on rRNA production and angiogenesis, ANG plays important roles in cell growth and tumour progression." (PMID 38421827, 2024). "Overexpression of miR-409-3p in fibrosarcoma cell lines led to reduced ANG expression, resulting in decreased tumor growth, vascularization, and metastasis both in vitro and in vivo." (PMID 39594601, 2024). "The MP releases various factors (e.g., VEGF-A, PDGF-AA, and angiogenin) at the tumor cell surface that can promote peritumoral angiogenesis and thereby tumor growth." (PMID 38675197, 2024). "ANG plays dual roles in promoting tumour cell proliferation and angiogenesis in tumour growth and is also an essential permissive factor for VEGF, aFGF, bFGF, and EGF in promoting angiogenesis." (PMID 38421827, 2024). "By promoting rRNA transcription through nuclear translocation, ANG promotes tumour cell proliferation and angiogenesis." (PMID 38421827, 2024). "The urinary levels of ANG and angiostatin and the marker of oxidative stress, 8-iso-prostaglandin F2α (8-iso-PGF2α), the tumour progression marker ɣ-synuclein as well as IL-13 were shown to increase with the development of BC." (PMID 37052868, 2023). "In juxtatumors, ANG expression was restricted to certain groups of PT, whereas ANG was more widely expressed in ccRCC tumor areas." (PMID 38025776, 2023). "Angiogenin (ANG) is an angiogenic factor that has been reported to induce tumor progression by stimulating both cancer cell proliferation and angiogenesis." (PMID 37445908, 2023). "The ADAM8 Metalloproteinase (MP) domain promoted release of various factors (e.g., VEGF-A, PDGF-AA, angiogenin) from the tumor cell surface that mediate angiogenesis and tumor growth." (PMID 37568162, 2023). "For patients with malignant tumors, ANG upregulation in their tumor tissues was usually accompanied by a significant unfavorable prognosis." (PMID 37928479, 2023). "Angiogenin, a member of the ribonuclease A superfamily, not only activates endothelial cells and induces tumour angiogenesis but also targets tumour cells to promote cell migration and invasion." (PMID 37480078, 2023). "PLXNB2 is the functional cell surface receptor of ANG, which was originally identified as a tumor angiogenic factor." (PMID 35335125, 2022). "Angiogenin (ANG) is the first human tumor-derived angiogenic protein, which can promote angiogenesis and tumor growth." (PMID 35463945, 2022). "Activation of the signaling pathways of VEGF and ANG is considered to be a critical step in tumor angiogenesis." (PMID 35805939, 2022). "As the first human tumor-derived angiogenic protein, ANG serves as an important regulator both in angiogenesis and tumorigenesis." (PMID 35463945, 2022). "Angiogenin (ANG), a member of the RNase family that was initially discovered to be a tumor angiogenesis factor, is one of the most potent angiogenic factors and promotes the growth, survival, migration, and invasion of endothelial cells." (PMID 35955934, 2022). "Angiogenin, an angiogenic factor released by tumour cells, acts as a secreted stress-activated ribonuclease, producing tRNA-derived stress-induced RNAs (tiRNAs)." (PMID 35098996, 2022). "The phage nanofiber fd388‐AR‐WV can home to the breast tumor in situ and capture the angiogenin secreted by the tumor, thereby significantly preventing tumor angiogenesis." (PMID 35246962, 2022). "These suggest that ANG promotes cell motility and proliferation, which are both critical in processes in tumor growth and development, through extracellular as well as intracellular pathways involving the actions of actin." (PMID 35463945, 2022). "The actions of angiogenin were first described in tumor angiogenesis, but it also acts as a neuroprotectant in neurodegenerative diseases in vitro and in vivo." (PMID 34234733, 2021).
tumor (continued). "Second, ANG is well-known for promoting tumor angiogenesis under hypoxia, but it is reported that ANG-induced tsRNAs (derived from tRNA-Val-CAC and tRNA-Gly-GCC) act as negative regulators of angiogenesis in endothelial cells under hypoxia." (PMID 33588913, 2021). "Studies have demonstrated ANG to induce cell survival, proliferation, endothelial tube formation, xenograft angiogenesis, cell migration, angiogenesis, and tumour suppressor gene expression." (PMID 34512316, 2021). "Studies have found that HBV can be involved in the translation and nuclear translocation of angiogenin (ANG) through IL-6-mediated pathways, thereby promoting tumor cell proliferation." (PMID 34976809, 2021). "Mechanistically, the generation of 5’tiRNA-His-GTG seems to be a responsive process of tumor hypoxic microenvironment, and it is regulated via the HIF1α/angiogenin (ANG) axis." (PMID 33588913, 2021). "Serum vascular endothelial growth factor (VEGF)-A, angiogenin, and angiopoietin-1 (Ang-1), which are secreted by tumors in the body and thus indicate total tumor growth and aggressiveness, are considered biomarkers for tumor angiogenesis." (PMID 33794813, 2021). "Serum biomarkers of tumor angiogenesis, including vascular endothelial growth factor-A (VEGF-A), angiogenin, and angiopoietin-1, were measured by enzyme-linked immunosorbent assays simultaneously." (PMID 33794813, 2021). "Previous studies on other tumours have found ANG expression to be a prognostic factor for tumour recurrence, tumour progression, and OS." (PMID 34512316, 2021). "Combinatorial therapy of docetaxel (DTX) and a PLXNB2 mAb inhibited chemo-resistant CSC tumors and delayed disease recurrence, suggesting that targeting ANG/PLXNB2 is an effective means for eliminating quiescent CSCs in tumor therapy." (PMID 31942000, 2020). "Next, to dissect the mechanism of how ERβ can increase the HUVEC tube formation, we focused on tumor angiogenesis-related genes, including Angiogenin, ANGPT-2, bFGF, EGF, HB-EGF, HGF, Leptin, PLGF, and VEGF-A35." (PMID 32409702, 2020). "More recently, the ANG/Tie2 receptor signaling are considered together with VEGF the main regulators of different mechanisms of tumor vascularization that act in a complementary and coordinated way." (PMID 31354524, 2019). "Originally, human ANG was isolated as an angiogenesis factor of tumour origin; however, the expression of ANG by cells of various tissues suggests that its functions are not limited to neovascularization." (PMID 31572192, 2019). "A synthetic compound, terrain, was demonstrated to inhibit tumor cell proliferation in head and neck cancer by suppressing hRNase5/ANG production." (PMID 30449278, 2018). "Angiogenin (ANG) is the tumor-growth promoter due to its ability to stimulate the formation of new blood vessels." (PMID 27437030, 2016). "Another study revealed a potential tumor suppressor miRNA, miR-409-3p that downregulated angiogenin expression levels leading to cell death and tumor regression." (PMID 26137468, 2015). "Aminoglycoside antibiotics neomycin and neamine have been shown to block nuclear translocation of ANG thereby abolishing the biological activity of ANG and inhibiting cancer cell proliferation as well as tumor angiogenesis." (PMID 25659096, 2015). "Surface actin in endothelial cells has been demonstrated to serve as a receptor for angiogenin, plasminogen and tissue plasminogen activator, proteins which play central role in angiogenesis and tumor progression." (PMID 25815360, 2015). "Human angiogenin (ANG) was originally isolated over 25 years ago as a tumour-derived protein with angiogenic properties." (PMID 22970115, 2012). "Interaction of borderline significance (P ≤0.15) was observed for CK14, Angiogenin, and β-Catenin, with a trend towards docetaxel benefit for patients with a marker-positive tumor." (PMID 22044691, 2011).
tumor (continued). "Further studies using mouse models are warranted to elucidate the roles of ANG on cell migration during tumor angiogenesis or cancer cell metastasis." (PMID 22194915, 2011). "In humans, angiogenin (RNase 5) is an inducer of neovascularization, and plays an important role in tumor growth." (PMID 21205197, 2011). "Proteins that induce pathologic angiogenesis in other systems include angiogenin, a small protein involved in angiogenesis in tumor metastases." (PMID 21364907, 2011). "Many molecules such as angiogenin, interleukin 8 and 10, platelet-derived endothelial growth factor, fibroblast growth factor, and angiopoetins have a role in tumor angiogenesis." (PMID 20546613, 2010). "Angiogenin is a 14 kD protein, initially isolated as a tumour-cell secreted product but subsequently found to be a normal constituent of human plasma." (PMID 2457389, 1988). "Notably, although VEGF has been mainly used as the main target for the treatment of aberrant blood vessel growth in the past, the ANG-TIE-2 pathway has also gradually shown its potential in anti-tumor induced angiogenesis." (PMID 40260291, 2025). "In summary, ANG may play a two-fold role in tumor angiogenesis or inhibition, while the study of ANG function is dominated by ANG1 and ANG2." (PMID 40260291, 2025). "While the VEGF pathway has long been the primary focus of angiogenesis studies, accumulating evidence indicates that the ANG-Tie axis plays a critical role in vascular stability, tumor microenvironment remodeling, and drug resistance, sometimes functioning independently of VEGF signaling." (PMID 40260291, 2025). "VEGF and angiogenin also play roles in angiogenesis and tumor formation." (PMID 39563017, 2024). "Therefore, inhibiting ANG in tumour treatment has advantages over previous single angiogenic factor inhibitors." (PMID 38421827, 2024). "ANG inhibitors (neutralizing antibodies or small chemical compounds blocking angiogenin nucleus translocation) have already been described to inhibit tumor growth in vitro and in vivo, but further studies in the context of ccRCC are needed to evaluate their therapeutic potential." (PMID 38025776, 2023). "In addition, treatment of HUVEC with rhIL30 substantially increased the basal release of ANG, therefore confirming the ability of tumor membrane-anchored IL30 to regulate the endothelial production of angiogenesis factors." (PMID 38087324, 2023). "Angiogenin is a key protein involved in neovascularization/angiogenesis, thus the up-regulation could indicate a survival mechanism being initiated by the tumour." (PMID 37760543, 2023). "Furthermore, the recruitment of bone marrow-derived cells (BMDCs) to tumours for vasculogenesis is essential for tumour angiogenesis, which is found to involve NF-κB-mediated enhanced expression of IL-8 and angiogenin." (PMID 36899924, 2023). "Functional blocking of ANG with antibodies, enzymatic inhibitors, nuclear translocation inhibitors, siRNAs, or nanofibers could prevent tumor angiogenesis and progression and result in targeted cancer therapy." (PMID 35463945, 2022). "Despite this, ANG has been considered as an important therapeutic target and several small-molecule inhibitors of ANG and an anti-ANG monoclonal antibody have demonstrated for anti-tumor activity." (PMID 33525475, 2021). "Particularly, tumor-infiltrating NK cells expressed higher levels of VEGF, IL-8, matrix metallopeptidase 9 (MMP9), placental growth factor (PlGF) and angiogenin, which, collectively participate in tumor angiogenesis, tumor microenvironment remodeling and tumor growth." (PMID 34445750, 2021). "In order to enhance the blood flow to meet the nutrient and oxygen demands of tumor growth, tumor cells generally secrete angiogenic factors, such as angiogenin, matrix metalloproteinases (MMPs), and vascular endothelial growth factors (VEGFs), to stimulate local neovascularization." (PMID 34681857, 2021).
tumor (continued). "h-ANG, also known as ribonuclease 5 (RNase 5) because it is included in the secretory pancreatic-type RNase super-family, is a 123 residue (14.1 kDa) protein present in plasma, cerebrospinal and amniotic fluid and in tumor microenvironments." (PMID 33535464, 2021). "CEBPB and POU2F1, which are transcription factors for miR-542-3p, were shown to be suppressed by angiogenin, which might function as a new tumor-endothelial cell signal pathway." (PMID 34778378, 2021). "Since previous studies have indicated tumour recurrence to be related to radio-resistance, these findings collectively indicate that ANG expression may be an important biomarker of radio-resistance in patients with NPC." (PMID 34512316, 2021). "Its ability to induce tumor neovascularization through a potent angiogenic activity is ANG's best characterized function and provided the first major support for Folkman's tumor growth hypothesis." (PMID 32111867, 2020). "This fact and the demonstration of the relationship between angiogenin and the degree of tumor aggressiveness may indicate a relationship between ANG and the development of cancer, including BC." (PMID 33343662, 2020). "An additional important parameter regarding tumour progression, which we examined, was ANG." (PMID 30828780, 2020). "The study noted the involvement of ANG in the tumor formation process." (PMID 33343662, 2020). "The difference in tumor-growth kinetics between anti-ANG and anti-EGFR agents may warrant further exploration." (PMID 31539075, 2019). "On the other hand, hRNase5/ANG originating from endothelial cells or fibroblasts may interact with EGFR on the cell surface of tumor cells which may result in oncogenic transformation via a paracrine pathway." (PMID 30449278, 2018). "Under hypoxic conditions, hRNase5/ANG is upregulated in certain tumor cells." (PMID 30449278, 2018). "Interestingly, both Ranpirnase and Amph display antiviral and anti-tumour activities, which suggested additional substrates beyond tRNAs for these enzymes, while ANG has the opposite effect through its angiogenic activities thereby promoting tumour growth." (PMID 30563140, 2018). "Hence, the evaluation of angiogenin concentration in tumour tissues and serum can be clinically useful for early diagnosis, as well as for monitoring tumour growth and progression." (PMID 29261171, 2017). "Angiogenin was the first human tumor-derived protein with in vivo angiogenic activity." (PMID 28041877, 2017). "Moreover, the angiogenin levels are reduced in cancer patients undergoing successful treatments, while are increased after tumour recurrence." (PMID 29261171, 2017). "Therefore, the study provides novel evidence that ANG plays an important role in the promoter activation of the tumor oncogenic gene MMP2, which likely contributes to ANG oncogenic activity." (PMID 27317771, 2016). "However, when the delayed treatment group is followed for 28 days, the tumor seems to acquire resistance to treatment, leading to tumor growth and increased expression of factors such as angiogenin, angiostatin, angiopoietin-1/2, EGF-R and IGF-1." (PMID 25549350, 2014). "Recently ANG has been reported to regulate the proliferation of cancer cells including HeLa cells and PC-3 cells directly, indicating that ANG regulates the activities of both vascular cells and cancer cells during tumor development." (PMID 23977052, 2013). "Second, ANG showed tight associations with most canonical immune checkpoints, such as PD1, CTLA4, and TIM3, suggesting that ANG might interact synergistically with these checkpoint members, all of which have been identified to play a suppressive effect on anti-tumor immunity." (PMID 37928479, 2023). "DICER1 codes for the Dicer protein, which cleaves double stranded pre miRNA into miRNA which can then go on to regulate gene expression, many miRNAs have been associated with tumorigenesis in HNSCC and herefore, in contrast to ANG, may be an indication of the tumour becoming less active." (PMID 37760543, 2023).